MIR323A (microRNA 323a)
Synonyms: hsa-mir-323; MIR323; MIRN323; hsa-mir-323a; mir-323a
Gene: MicroRNA gene on chromosome 14 (101,025,732 to 101,025,817, forward strand). Ensembl gene ENSG00000199069.
Gene Ontology:
Biological process: miRNA-mediated post-transcriptional gene silencing
Cellular component: RISC complex
Homologues: Orthologues: chimpanzee ptr-mir-323 (100% identical), guinea pig MIR323A (99% identical), mouse Mir323 (98% identical), rat Mir323 (98% identical), macaque MIR323A (92% identical), pig MIR323A (90% identical). Paralogues in human: MIR323B (77% identical), MIR154 (67% identical), MIR410 (67% identical), MIR496 (63% identical), MIR656 (63% identical), MIR1185-1 (62% identical), MIR487B (62% identical), MIR494 (62% identical), MIR487A (60% identical), MIR1185-2 (59% identical), MIR382 (58% identical), MIR409 (58% identical), and 4 more.